FOXP3 (forkhead box P3)
Diseases named in the same sentence as FOXP3 in open-access papers (continued):
Sharing a sentence is not in itself a finding about the gene and the disease.
cancer (continued). "For example, in a study of Interferon regulatory factor 4 (IRF4) with effector Treg differentiation and immune suppression in cancer, Foxp3EGFP-Cre-ERT2 mice were crossed with Irf4-floxed mice to allow for the specific deletion of Irf4 in Foxp3+ cells following TAM treatment." (PMID 36009853, 2022). "On the same tissue section, six cancer and immune markers were detected simultaneously, including a L-R pair (PD-1 and PD-L1), PanCK (epithelial cancer marker), CD8 (T cell marker), CD68 (Macrophage marker), FoxP3 (T regulatory cell marker)." (PMID 35967449, 2022). "In the current study, in the non-carcinoma biliary tract tissues, only naïve CD4+ and naïve CD8+ T cells were detected, whereas in cancer tissues, 4 distinct T cell subclusters were identified, as the emergence of cytotoxic CD8+ T cells and FOXP3+ Treg cells." (PMID 35219893, 2022). "The only study using CD4 and CD25 rather than FOXP3 to delineate Tregs did so because the aim was to investigate FOXP3 not only in Tregs, but also in cancer cells." (PMID 35740658, 2022). "In this review, we are going to discuss the potential connection between non-lymphoid FOXP3+ regulatory T cell dynamics and the new emerging and well-established hallmarks of cancer, especially on the immune escape of solid tumours." (PMID 36569832, 2022). "In cancer, the TAM-inducible Foxp3 knockout model is also being used to study Tregs." (PMID 36009853, 2022). "Double immunostaining of CXCR4/FOXP3 correlated with American Joint Committee on Cancer T-stage, independent of age or Ki67 index (P<0.01)." (PMID 35358193, 2022). "As FOXP3 is primarily expressed in the nucleus, FOXP3 has never been considered as a viable target to deplete Tregs in cancer." (PMID 36405718, 2022). "In another case of MIA (TD6), the cancer cell subtypes enriched in the cancer region, including Clara-like cancer cells (Epi-C1), NK cells (T/NK-C4: GNLY and T/NK-C5: NKG7), Tregs (T/NK-C6: FOXP3) and mast cells (Mye-C0: TPSB2, Mye-C9: CPA3), were also located in the cancer region." (PMID 36434043, 2022). "Although Foxp3 is considered as a specific marker of CD4+ regulatory T cells, it was also reported to express in non-Treg immune cells as well as non-immune cells, including CD8+ T cells, γδ T cells, NKT cells, B cells, macrophages, and cancer cells." (PMID 35967422, 2022). "We suggested to carefully balance the suppressive and non-suppressive roles when considering FOXP3 as a target against cancer." (PMID 34006632, 2021). "Hypoxia upregulates the infiltration levels of Treg cells by increasing the expression of the FOXP3 transcription factor, TGF-β, and CCL28, which may inhibit the anti-cancer immune responses." (PMID 34484235, 2021). "Expression level of miR-155, SOCS1, TAB2, and Foxp3 in cancer cachectic patients considering the cachexia severity, regardless of the cancer type." (PMID 34900737, 2021). "Also, the key roles of the genes selected by the Laplacian score including IFN-γ, Foxp3, IL-4, BCL-2, Oct4 and survivin in the development of various cancers and their prognostic value have been clinically confirmed." (PMID 34181334, 2021). "Among tumor-infiltrating lymphocytes (TILs), the number of CD8+ is significantly lower in those cases carrying IPF, whereas the CD8+/Foxp3+ T cell ratio was higher than that in the non-IPF cancer population." (PMID 33809111, 2021). "As the numerically dominant Treg population in the tumor microenvironment (TME), CD4+CD25+Foxp3+ cells have been extensively studied in cancers, unlike CD8+CD28− Tregs." (PMID 34831195, 2021). "Furthermore, high SUVmax was strongly correlated with positive PD-L1 expression on cancer cells, low CD8 + TIL counts, and high Foxp3 + TIL counts." (PMID 33712681, 2021). "Recently, researchers found that the expression of FOXM1 was positive correlated with FOXP3 (the specific molecular marker of Tregs) and FOXM1 may induce immune suppression via recruiting FOXP3 positive Tregs in cancer therapy." (PMID 33892811, 2021).
cancer (continued). "The density of CD4+ and CD4+ Foxp3-positive T-cells in brain metastases with radiation was statistically higher in the carcinoma and stromal areas compared with those without radiation (p = 0.0343, p = 0.0173)." (PMID 34647108, 2021). "With regard to the primary lesions, the densities of CD4+ T-cells, CD8+ T-cells, CD204+ cells, and CD4+Foxp3+ T-cells in carcinoma and stromal areas were not statistically correlated with OS by linear regression models." (PMID 34647108, 2021). "The densities of CD4+Foxp3+ cells were positively correlated with OS in the carcinoma area of the brain metastases, but not in the stromal areas." (PMID 34647108, 2021). "TGF-β is a cytokine that induces the Foxp3+ phenotype in lymphocytes, while IL10 is an immunosuppressive factor whose increased concentration has been observed in chronic inflammation as well as in cancer." (PMID 32488850, 2020). "However, a majority of studies use antibodies targeted to key surface markers to broadly identify major TIL subsets in cancer such as CD20 (B cells), CD3 (T cells), CD4 & CD8 (T cells) and FOXP3 (Regulatory T cells or Treg)." (PMID 33013886, 2020). "Considering that cancer-FOXP3 has been identified as a biomarker for poor prognosis in NSCLC, it is rational to propose that FOXP3-initiated CCL5-CCR5 interactions may also participate in Treg cell migration in NSCLC." (PMID 32425930, 2020). "CD4+CD25+ FOXP3+Helios+, CD4+CD25-FOXP3+Helios+and CD25+FOXP3+CD73+CD39+Tregs wereexpanded after co-culturing of T cells with both cancer-ASCs and normal-ASCs, while they were statistically significantonly in the presence of cancer-ASCs (P<0.05)." (PMID 31721539, 2020). "Nonetheless, recently work has demonstrated that a population of FOXP3+ non-Treg cells are also found in cancer." (PMID 33013886, 2020). "Nuclear factor FoxP3 is the most important part in the specification of Treg cells, so both the percentage and their general number among CD4-positive cells in the blood and cancer tissue were established according to this factor." (PMID 30944830, 2019). "However, controlling B cells in the TME helps interrupt the initiation of cancer-induced immunosuppressive events, such as the TGF-β-dependent conversion of FoxP3+ cells to support and promote metastasis." (PMID 31906017, 2019). "A recent meta-analysis of 76 studies encompassing 17 types of cancer, including 15,512 cancer cases, suggested that in aggregate FoxP3+ Tregs had a negative effect on survival." (PMID 30926808, 2019). "The number of TIN was significantly correlated with that of CD8+ T cells, suggesting that those cells cooperate to induce inflammation affecting cancer invasion, although there were not apparent associations in TIN with CD3+ and FOXP3+ cells." (PMID 31456937, 2019). "Analysis of prognostic significance of FoxP3+ Tregs has led to highly variable results between different cancer types and, overall, a negative prognostic effect was associated with Tregs." (PMID 31546872, 2019). "Verifying the corresponding in vivo relationship between Sdc-1 and Foxp3 mRNA expression, we found a negative correlation in carcinoma tissue of IBC patients." (PMID 31145753, 2019). "Since FOXP3, miR‐198 and MYC do not only exist in liver cells, whether this study could be repeated in other types of cancers remains unclear." (PMID 30378283, 2018). "Cancer CD4, CXCL13, and FOXP3 expression correlated positively with each other (P ≤ 0.001)." (PMID 29482642, 2018). "In cancer, the expression of TIM-3 on T lymphocytes may promote T cell exhaustion and the expansion of suppressive CD4+FoxP3+ regulatory T cells and CD11b+Gr-1+ myeloid-derived suppressor cells (MDSC)." (PMID 28674498, 2017). "Finally, CD26neg T cells from cancer patients contained Tregs, as they expressed less CD127 but greater CD39, FoxP3, and Helios." (PMID 29213079, 2017).
cancer (continued). "Analysis of a combination of CD4/CD8, CD25, CD127, and FoxP3 markers revealed a statistically significant increase in the frequencies of Tregs within both the CD4 and CD8 subsets of circulating lymphocytes in patients with CIN3 and stage IA cancer." (PMID 29075318, 2017). "We have recently reported that Tregs co-expressing FoxP3 and Helios represent a functional subset with stronger suppressive characteristics, and FoxP3/Helios co-expression with GARP/LAP can be used to identify expanded Treg subsets in cancer patients." (PMID 28388539, 2017). "Here the induction of FOXP3 degradation in Treg cells provides a potential method that enables transient inhibition of suppressive Treg cells, and thus USP21 is a potential drug target for future anti-cancer immunotherapy." (PMID 27857073, 2016). "Peripheral blood of NSCLC patients is characterized by a significantly higher percentage of Th17 (CD4+IL-17+) and Treg cells (CD4+CD25+FoxP3+) compared to individuals without cancer." (PMID 27784305, 2016). "Positive for progression but not clinical outcomes: infiltration of Foxp3+ cells was increased in cancer compared to non-atrophic benign tissue but did not correlate with Gleason score." (PMID 26217583, 2015). "This suggests that cancer cell-derived Foxp3 entry into the nucleus is independent of exogenous stimuli." (PMID 25779374, 2015). "In addition, cancer-specific survival rates for patients were analyzed in correlation with T cells (CD4+, CD8+, FoxP3+ and IL-17+ T cells)." (PMID 25968569, 2015). "FOXP3 expression has been recently described in normal cells and in non-hematopoietic-derived cancer cells, suggesting that FOXP3 biological effects are not restricted to Foxp3+CD4+ T cells." (PMID 26604855, 2015). "Importantly, the proportion of FOXP3+ CD4+ cells remains stable, making it suitable for use as a biomarker for cancer posttransplantation." (PMID 25250867, 2014). "Furthermore, higher numbers of CD3+ T cells as well as low expression of FoxP3 and L1CAM in carcinoma cells tended to be correlated with prolonged patient survival." (PMID 24797069, 2014). "Our findings strongly suggest that Foxp3 expression mediated by cancer cells rather than by Treg cells contribute to disease progression." (PMID 23382847, 2013). "Furthermore, it was found that FOXP3 decreased the invasive ability of MCF-7 cells, thereby potentially decreasing cancer malignancy." (PMID 24155921, 2013). "In contrast, there was no or negligible Foxp3+ Treg expression found in Foxp3 positive cancer tissue (arrow)." (PMID 23382847, 2013). "Despite a clear role in Tregs, FOXP3 protein expression is not restricted to the lymphocyte lineage but is also present in normal and cancer cells of non-hematopoietic origin." (PMID 24350059, 2013). "Despite a clear role for FOXP3 in Tregs, FOXP3 protein expression is not restricted to the lymphocyte lineage but is also present in cancer cells of non-hematopoietic origin." (PMID 23341929, 2013). "Immunohistochemistry showed increased Foxp3+ Treg expression in Foxp3 negative cancer stromal tissue (arrow)." (PMID 23382847, 2013). "Although Foxp3 was thought to be unique marker for Tregs, it was found to be expressed also by nonlymphocytic nonhematopoietic cells and by cancer cells." (PMID 22323550, 2012). "Thus, we inspected the gene expression levels of the examined genes (CD4, CD25, FOXP3, TGF-β, IFN-γ, IL-10, CTLA-4, PD-1, PD-L1, ARG1) in the CRC patients and confirmed they were all upregulated in the cancer patients." (PMID 22496728, 2012). "Double CXCR4/FOXP3 immunoperoxidase staining was performed to evaluate CXCR4 positive Treg infiltration in whole stained sections from 10 grade 3 basal-like and 11 grade 3 luminal cancers." (PMID 21521526, 2011). "The higher proportion of Foxp3+ cells in the SLN of the cancer patients was neither due to increased infiltration of CD3+ T-cells nor CD4+ T-cells." (PMID 19604349, 2009).
cancer (continued). "Similarly, the ratio of Foxp3+ cells to CD4+ cells was higher, 0.29, in the cancer patients than in the controls, 0.14, p < 0.001." (PMID 19604349, 2009). "In CA-CRC, FOXP3+ Tregs suppress the immune system’s ability to fight cancer, while IL-17-producing Th17 cells promote the growth of epithelial cells, the formation of blood vessels, and cell resistance to death." (PMID 41153383, 2025). "Importantly, CAIX expression was also associated with PD-L1 expression and other immune-inhibitory signatures (FOXP3, TGF-β, LAG-3, TIM-3), supporting the notion that metabolic stress directly contributes to immune dysfunction in the TME, allowing for cancer progression." (PMID 41226466, 2025). "Therapeutically, strategies aiming to restore CASP1 activity, deplete or inhibit FOXP3+ Tregs, or target PDIA3-related antigen presentation defects could enhance immune surveillance and improve responsiveness to immunotherapy in multiple cancer types." (PMID 41150760, 2025). "Therefore, we hypothesize that these Foxp3+ Tregs may promote HCC progression by inhibiting T-cell proliferation and IFN-γ production in cancer patients." (PMID 40297156, 2025). "Recent reports suggest that FOXP3 is also expressed in normal non-lymphoid cells or cancer cells, indicating that the transcriptional regulatory role of FOXP3 may be broader than initially thought." (PMID 40182619, 2025). "This STRING interactome indicates that FOXP3 is not only a Treg marker but may also play multiple roles in inflammatory processes present in the TME (Section 5 and Section 6) and NSCLC cancer progression (Section 7 and Section 8), which will be discussed later in this manuscript." (PMID 38674427, 2024). "Notably, protein targets associated with B cells (CD20), macrophages (CD68), Treg cells (PD-1, FOXP3), and NK cells (CD56) exhibited significant differential expression within CD45+ segments located in regions of immune-rich cancer cell islet compared to the adjacent stromal leukocytes." (PMID 38785789, 2024). "Via rising distal natural killer (NK) cells and inducing cancer‐specific CD8+ T cells with specific memories, lowering pro‐inflammatory cytokines including TNF and IL‐17, and through boosting the quantity of Th17 lymphocytes and FOXP3 in circulation within cancer mattresses." (PMID 38571678, 2024). "Thus, FOXP3 and TIGIT are considered attractive targets for cancer immunotherapy." (PMID 37573372, 2023). "Nowadays, it is known that the FOXP3 expression is not exclusive of lymphoid lineage as it has been detected in epithelial cells from the breast, lung, prostate, and retinal tissue, as well as in cancer cells." (PMID 36672296, 2023). "FOXP3 was not expressed in cancer cells, but mainly in immune cells." (PMID 36550816, 2022). "It is well documented that FOXP3, as a critical master transcription regulator for Treg cell development and function, helps control the activities of various genes (such as oncogenes SKP2 and HER-2/ErbB2) related to the cancer development of the breast and prostate." (PMID 34768829, 2021). "We quantified the frequencies of CD4+CD25+FOXP3+ Tregs in all groups and found a significant reduction in Tregs in the C + I vaccine group compared with PBS in both TDLNs and the spleen, reversing the immune-suppressive microenvironment in mice injected with cancer cells." (PMID 33961792, 2021). "However, a recent contradictory result showed that FOXP3+ Tregs were not affected in cancer patients treated with anti‐CTLA4 therapies." (PMID 34185431, 2021). "Our approach refined cell counting by excluding FoxP3+ cells of non-lymphocyte or unknown origin, e.g., cancer cells or immune cells negative for other markers." (PMID 34771707, 2021). "In fact, studies have described a negative relationship between peripheral CD4+FoxP3+ regulatory T cell levels and clinical response to adoptive immunotherapy of human cancer, suggesting that Tregs mediate the inhibitory effects of adoptive immunotherapy on human tumors." (PMID 32964058, 2020).
cancer (continued). "The negative effect of Foxp3+ IL-17+ T cells on cancer prognosis may be due to the fact that these cells promote cancer growth." (PMID 32121394, 2020). "In addition, tumors from non-responder mice showed more abundance of Foxp3+ regulatory T cells and IL-10 than responders to cancer chemotherapy such as doxorubicin administration." (PMID 31653148, 2019). "The results of simultaneous FoxP3-staining indicate that the very simple classification that is based on CTLs alone might not suffice to define groups predicting response to cancer therapies." (PMID 31546872, 2019). "Moreover, there is a negative correlation between expression of Sdc-1 mRNA and IL-4, IL-17 and Foxp3 mRNA levels in carcinoma tissues of IBC and that correlation was reversed in non-IBC." (PMID 31145753, 2019). "Among various FoxP3 and Helios Treg subsets, the proportion of FoxP3−Helios+ Treg subset was relatively high in PBMCs of HD and CRC patients, whereas FoxP3+Helios+ Treg subset proportion was highest in TILs (54%) compared to NILs (26.3%), PBMCs (26.2%) of cancer patients." (PMID 28603527, 2017). "Despite a CD4+ bias, there was no increase in CD4+ CD25+ CD27− FoxP3+ Tregs, which may have a negative effect on anti-cancer potency of adoptively transferred T cells." (PMID 28239467, 2017). "The cancer cells that undergo SNAIL-mediated EMT are considerably more metastatic than their parental cells, and this has been attributed to the emergence of T regulatory (Treg) CD4 cells expressing Foxp3 (Forkhead Box P3), which induces immunosuppression in these cells." (PMID 29379795, 2017). "The marked increase in CD4+FoxP3+ Treg levels in TT compared to NT and peripheral blood of CRC patients in our study was in accordance with previously published reports from other groups, where an expansion in Treg levels in TILs in various cancers including CRC was demonstrated." (PMID 28603527, 2017). "Indeed, our own data show that during stimulations of naïve T cells in the absence of any cancer cell supernatant, around 30% of T cells upregulate FOXP3 expression." (PMID 28239749, 2017). "The high expression of CD39 and Foxp3 was also reported in some other cancers, not specific to HCC." (PMID 27749555, 2016). "The potential role of the FoxP3+Helios− Treg subset in these cancers could be less significant as they were not expanded in cancer patients, at least in peripheral blood." (PMID 26885615, 2016). "Natural regulatory T cells (Tregs), identified by the expression of Foxp3, play an important role in down-regulating immune responses and an imbalance between numbers of Tregs and conventional CD4 (Tconv) and CD8 T cells contributes to outcomes in cancer and autoimmune and infectious diseases." (PMID 23029447, 2012). "Notably, the population of liver-resident Tregs (CD4+Foxp3+) expands during MASH, with FOXP3+ Tregs demonstrating the ability to suppress the proliferation and activity of CD8+ T cells and Th1 cells, which play a crucial role in immune surveillance against cancer." (PMID 40370443, 2025). "Moreover, the population of CD4+CD25+Foxp3+ Tregs and Gr1+CD11b+ MDSCs was not increased by RT plus iPSC-based cancer vaccines, indicating that this therapeutic strategy might not induce Treg-mediated suppression of TAA-reactive T cells." (PMID 38821980, 2024). "Therefore, we examined expression of IL-17, Foxp3, IL-4 and Sdc-1 transcript levels in carcinoma tissue of non-IBC and IBC patients and tested whether there is any correlation among them." (PMID 31145753, 2019). "Thus, those strategies able to inhibit FOXP3 dimerization, its interaction with AML1 or to modify the FOXP3 interactome might have important consequences on Treg activity and thus could be exploited as therapeutic agents in cancer." (PMID 29069740, 2017).